PPIL2 (peptidylprolyl isomerase like 2)
Description:
Has a ubiquitin-protein ligase activity acting as an E3 ubiquitin protein ligase or as an ubiquitin-ubiquitin ligase promoting elongation of ubiquitin chains on substrates. By mediating 'Lys-48'-linked polyubiquitination of proteins could target them for proteasomal degradation. May also function as a chaperone, playing a role in transport to the cell membrane of BSG/Basigin for instance. Probable inactive PPIase with no peptidyl-prolyl cis-trans isomerase activity. As a component of the minor spliceosome, involved in the splicing of U12-type introns in pre-mRNAs (Probable).
Synonyms: Cyp60; hCyP-60; UBOX7; CYC4; Cyp-60
Tractability: Small molecule: a structure with a bound ligand is known. Antibody: its Gene Ontology location is reachable by antibodies, with high confidence. PROTAC: UniProt records ubiquitination sites on it; ubiquitination databases record sites on it; its protein half-life has been measured.
Target class: Enzyme; Transferase
Gene: Protein-coding gene on chromosome 22 (21,666,000 to 21,700,015, forward strand). Ensembl gene ENSG00000100023.
Subcellular location: Nucleus
Subcellular location (Human Protein Atlas): Nucleoplasm
Pathways (Reactome):
Hemostasis: Basigin interactions
Metabolism of RNA: mRNA Splicing - Major Pathway
Gene Ontology:
Molecular function: peptidyl-prolyl cis-trans isomerase activity; protein binding; ubiquitin protein ligase activity; ubiquitin-ubiquitin ligase activity; ubiquitin-protein transferase activity
Biological process: protein localization to plasma membrane; protein polyubiquitination; mRNA splicing, via spliceosome; protein folding; protein ubiquitination
Cellular component: cytoplasm; nucleoplasm; nucleus; plasma membrane; spliceosomal complex; U12-type catalytic step 2 spliceosome; U2-type catalytic step 1 spliceosome; catalytic step 2 spliceosome; Golgi lumen
Genetic constraint (gnomAD): Loss-of-function variants: 52 observed, 79.17 expected, observed/expected ratio (o/e) 0.66, 90% interval 0.52 to 0.83. The upper end of that interval is the gene's LOEUF score, 0.83, which puts it in group 3 of 6, group 1 being the genes least tolerant of losing a copy. Missense variants: 590 observed, 700.67 expected, observed/expected ratio (o/e) 0.84, 90% interval 0.79 to 0.9. Synonymous variants: 245 observed, 264.31 expected, observed/expected ratio (o/e) 0.93, 90% interval 0.83 to 1.03.
Homologues: Orthologues: chimpanzee PPIL2 (99% identical), macaque PPIL2 (98% identical), guinea pig PPIL2 (94% identical), dog PPIL2 (93% identical), rabbit PPIL2 (91% identical), mouse Ppil2 (90% identical), pig PPIL2 (88% identical), rat Ppil2 (82% identical), tropical clawed frog ppil2 (78% identical), zebrafish ppil2 (76% identical), Drosophila melanogaster CG7747 (54% identical), Caenorhabditis elegans cyn-4 (49% identical). Paralogues in human: PPWD1 (28% identical), CWC27 (20% identical), NKTR (18% identical), PPIE (18% identical), PPID (16% identical), PPIG (16% identical), PPIL3 (16% identical), PPIL1 (16% identical), PPIL6 (16% identical), PPIA (15% identical), PPIF (14% identical), PPIB (14% identical), and 10 more.
Diseases named in the same sentence as PPIL2 in open-access papers:
PPIL2 is named in the same sentence as 15 diseases in open-access papers, as found by Europe PMC text mining. Sharing a sentence is not in itself a finding about the gene and the disease. The quoted sentences say what the papers report.
breast carcinoma (6 papers, 2018 to 2025). "PPIL2 is an ubiquitin ligase and probably participates in breast cancer metastasis in animal models because its downregulation led to increased migration of human breast cancer cells." (PMID 37869102, 2023). "But our data demonstrate that CsA prolonged PPIL2 half-life and increased PPIL2 abundance in breast cancer." (PMID 29352246, 2018). "Considering the role of PPIL2 on cell mobility, we focused on the function of PPIL2 in breast cancer metastasis." (PMID 29352246, 2018). "Taken together, our results show that PPIL2 changes cell morphology and represses cell migration and invasion in breast cancer cells." (PMID 29352246, 2018). "Herein, we demonstrate that PPIL2 suppressed metastasis in a breast cancer model by altering cell morphology and suppressing the epithelial–mesenchymal transition (EMT) process." (PMID 29352246, 2018). "In general, these results support our finding that PPIL2 acts as a crucial player in the suppression of metastasis in breast cancer." (PMID 29352246, 2018). "A χ2 analysis validated that PPIL2 expression was significantly correlated with breast cancer infiltration and lymphatic metastases (P < 0.05)." (PMID 29352246, 2018). "Analysis of tissue samples taken from breast cancer patients showed a significant correlation between the expression of PPIL2 and the degree of cancer invasion and metastasis." (PMID 29352246, 2018). "Although PPIL2 has been reported to potentially be involved in cell migration, its role in breast cancer is still unclear." (PMID 29352246, 2018). "214986_x_at (i.e., V14901) is the gene responsible for encoding peptidylprolyl isomerase like 2 (PPIL2), as tissue sample analysis from breast cancer patients showed a significant correlation between PPIL2 expression and the degree of cancer invasion and metastasis." (PMID 40319095, 2025). "Taken together, these results indicate that PPIL2 might have an important role in regulating EMT in breast cancer cells." (PMID 29352246, 2018). "In the present study, we aimed to explore the role of PPIL2 in breast cancer metastasis." (PMID 29352246, 2018). "In this study, we demonstrated that PPIL2 is a novel regulator of breast cancer metastasis." (PMID 29352246, 2018). "In conclusion, CsA induced PPIL2 accumulation in breast cancer cells." (PMID 29352246, 2018). "CsA also inhibited breast cancer migration and invasion, in a partially PPIL2-dependent way." (PMID 29352246, 2018). "PPIL2 contributed to F-actin arrangement in breast cancer cells." (PMID 29352246, 2018). "Taken together, these data support the hypothesis that PPIL2 is involved in breast cancer metastasis in our animal model." (PMID 29352246, 2018). "Collectively, these findings are consistent with the speculation that PPIL2 plays a partial role in the antimetastasis mechanism of CsA in breast cancer cells." (PMID 29352246, 2018). "It was demonstrated that PPIL2 takes part in CsA-mediated inhibition of EMT in breast cancer." (PMID 29352246, 2018). "Further investigations into PPIL2-mediated suppression of cancer metastasis may provide insight for extending the clinical use of CsA to breast cancer patients." (PMID 29352246, 2018). "Revealing the precise mechanism of the role of PPIL2 in the EMT process might give insight into the potential use of CsA in breast cancer." (PMID 29352246, 2018). "Furthermore, PPIL2 protein level and stability was upregulated after CsA treatment, indicating that PPIL2 might be involved in CsA-mediated repression of EMT in breast cancer." (PMID 29352246, 2018). "Recent studies have shown that PPIL2 affects the epithelial–mesenchymal transition (EMT) process through SNAl1 ubiquitination and degradation, which inhibits migration and invasion of breast cancer cells." (PMID 36092721, 2022). "U-box-type E3 ubiquitin ligase PPIL2 can inhibit EMT and invasion of breast cancer by interacting with the classical EMT transcription factor, SNAI1, to enhance its ubiquitin-dependent degradation." (PMID 36385010, 2022).
breast carcinoma (continued). "We provided a comprehensive model demonstrating that PPIL2 inhibits EMT and metastasis in breast cancer through cytoskeleton remodeling and by modifying SNAI1 ubiquitination." (PMID 29352246, 2018). "Upregulation of PPIL2 was reported to inhibit EMT and tumor invasion by interacting with the classical EMT transcription factor, SNAI1, to enhance its ubiquitin-dependent degradation in breast cancer." (PMID 34616428, 2021). "Moreover, elevated PPIL2 inhibited EMT and breast cancer invasion by interacting with the classical EMT transcription factor, SNAI1, to enhance its ubiquitin-dependent degradation." (PMID 29352246, 2018).
type I diabetes (2 papers, 2022 to 2023). "In type I diabetes (T1D), LIPS assays detect robust autoantibodies against a variety of known autoantigens including IA2, IA2-beta, and GAD65, as well as establishing new immunoassays for such targets such as tetraspanin-7 and PPIL2 and MLH1." (PMID 36979515, 2023).
anemia (1 paper, 2025). A reduction in the number of red blood cells, the amount of hemoglobin, and/or the volume of packed red blood cells. "Loss of Ppil2 in mouse hematopoietic cells in vivo leads to mild anemia." (PMID 40338661, 2025). "We found mild anemia and neutropenia in mice transplanted with Ppil2-deficient c-Kit+ cells." (PMID 40338661, 2025). "In this respect, the CRISPR/Cas9 knockout experiment in HSPCs followed by transplantation revealed mild anemia and cytopenia in the recipient mice, confirming Ppil2’s function in hematopoiesis." (PMID 40338661, 2025).
bipolar disorder (1 paper, 2023). A disorder of the brain that causes unusual shifts in mood, energy, activity levels and the ability to carry out day-to-day tasks. "Our finding of PPIL2 as a bipolar disorder driving gene is supported by this gene’s over-representation of rare protein truncating variants in the Bipolar Exome sequencing consortium data." (PMID 37267418, 2023). "However, we can identify five top genes at 22q11.2 associated with BMI (YDJC, CCDC116, PPIL2, THAP7, UBE2L3), primarily located outside the canonical CNV region (LCR D-E), three with bipolar disorder (TMEM191B, TUBA8, PPIL2), six with ASD (CLTCL1, AC004471." (PMID 37267418, 2023). "Bipolar disorder at 22q11.2 (with single genes models most often explaining variance) showed association with flanking genes on either side, TUBA8, TMEM191B, and PPIL2; PPIL2 appeared in most of the pairs, as well." (PMID 37267418, 2023). "A single gene was repeatedly contributing to top pairs for bipolar disorder at 16p11.2 (INO80E, 26% of top pairs) and schizophrenia at 22q11.2 (PPIL2, 42% of top pairs)." (PMID 37267418, 2023).
breast fibroadenoma (1 paper, 2018). "Based on the IHC scoring system defined in Materials and Methods, PPIL2 expression was lower in ductal breast carcinoma tissue compared to normal/pericarcinomatous and fibroadenoma breast tissue." (PMID 29352246, 2018). "To determine the clinical relevance of our in vitro observations, we analyzed the expression levels of PPIL2 by immunohistochemistry (IHC) in human breast tissue samples including five normal/pericarcinomatous samples, nine fibroadenoma samples, and 34 ductal carcinoma samples." (PMID 29352246, 2018).
ductal carcinoma (1 paper, 2018). "We further characterized PPIL2 IHC expression in 34 breast ductal carcinoma cases, and defined an IHC score of ≤3 as being negative." (PMID 29352246, 2018).
metastatic carcinoma (1 paper, 2018). A carcinoma which has spread from the original site of growth to another anatomic site. "We then chose five lungs with less metastatic carcinoma from the CsA group for PPIL2-level measurements." (PMID 29352246, 2018).
myeloproliferative neoplasm (1 paper, 2025). A clonal hematopoietic stem cell disorder, characterized by proliferation in the bone marrow of one or more of the myeloid (i.e., granulocytic, erythroid, megakaryocytic, and mast cell) lineages.
schizophrenia (1 paper, 2023). A major psychotic disorder characterized by abnormalities in the perception or expression of reality. "With this enhancement, we find one 22q11.2 gene (PPIL2) significantly associated with schizophrenia at a permutation-based threshold." (PMID 37267418, 2023).
cancer (6 papers, 2018 to 2025). A tumor composed of atypical neoplastic, often pleomorphic cells that invade other tissues. "Contradictory studies showed that PPIL2 functions as an oncoprotein or a tumor suppressor in different cancers, indicating its tissue-specific roles." (PMID 40338661, 2025). "A recent report showed that the upregulation of CD147 promoted metastasis of cholangiocarcinoma by modulating the EMT process, indicating an effect of PPIL2 on EMT in cancer cells." (PMID 29352246, 2018). "Given that PPIL2 is involved in cancer metastasis, we sought to confirm whether PPIL2 is related to DNA repair." (PMID 36092721, 2022). "In many studies, PPIL2 is involved in the metastasis of cancer cells." (PMID 36092721, 2022). "Interestingly, we observed lower PPIL2 levels in areas where cancer cells appeared to be traversing the basement membrane to the peripheral tissue." (PMID 29352246, 2018). "Recently, published data have shown that PPIL2 may play a role in cancer metastasis." (PMID 29352246, 2018). "Since cancer metastasis usually accompanies the EMT process, we sought to investigate the role of PPIL2 in EMT by examining the expression of typical EMT markers." (PMID 29352246, 2018).
tumor (4 papers, 2018 to 2026). "Furthermore, PPIL2 deficiency effectively hindered tumor growth in a xenograft mouse model." (PMID 42103231, 2026). "Critically, the tumor-suppressive effects induced by PPIL2 silencing were partially rescued upon c-Myc overexpression, confirming that PPIL2 exerts its oncogenic function predominantly through a c-Myc-dependent pathway." (PMID 42103231, 2026). "However, only mutations of PPIL2 and JAKMIP3 were identified in the progressive tumor and CTCs." (PMID 34616428, 2021). "Furthermore, the actin cytoskeleton is not only required for cell motility, but it is also important in protein transport and surface remodeling, which may suggest that PPIL2 plays an important role in proliferation, cell communication, and modulation of the tumor microenvironment in breast cancer." (PMID 29352246, 2018).
infection (2 papers, 2012 to 2022). The state of being infected such as from the introduction of a foreign agent such as serum, vaccine, antigenic substance or organism. "Conversely, using the PPIL2 shRNA infection reporter system to detect NHEJ and MMEJ activity, we observed that PPIL2 reduced NHEJ and MMEJ efficiency when PPIL2 was knocked down." (PMID 36092721, 2022).
PPIL2 also shares sentences with these, for which no sentence is quoted: Alzheimer disease (1 paper); hepatocellular carcinoma (1); neutropenia (1).